CXCR4 (C-X-C motif chemokine receptor 4)
Diseases named in the same sentence as CXCR4 in open-access papers (continued):
Sharing a sentence is not in itself a finding about the gene and the disease.
pancreatic cancer (continued). "CXCR4 activation contributes to the chemoresistant signature of pancreatic tumors by augmenting the production of Shh which, in an autocrine fashion, promotes EMT and a more stem cell-like state of PC cells." (PMID 34453639, 2021). "The chemokine receptor CXCR4 is hypermethylated in pancreatic cancer cell lines and primary pancreatic adenocarcinomas, while it is unmethylated in healthy pancreas tissue." (PMID 34901003, 2021). "HH signaling is responsible for chemoresistance in pancreatic cancer and its inhibition in combination with CXCR4 inhibition improved chemotherapeutic efficacy in pancreatic cancer." (PMID 33968932, 2021). "Another study confirmed that targeting CXCR4 can inhibit the growth of pancreatic cancer cells and increase the sensitivity of pancreatic cancer cells to gemcitabine." (PMID 34759953, 2021). "In PDAC, SDF-1α secretion by surrounding CAFs promotes chemoresistance mediated through paracrine SDF-1α/CXCR4 signaling and subsequently the IL-6 autocrine loop in pancreatic cancer cells." (PMID 33673405, 2021). "Blocking CXCR4 can effectively eliminate these survival signals and restore the sensitivity of pancreatic cancer cells to gemcitabine." (PMID 34759953, 2021). "CXCR4 is frequently expressed at high levels in pancreatic tumor cell lines, particularly those derived from metastatic lesions." (PMID 35008248, 2021). "It was also demonstrated that CD133+/CXCR4+ CSCs were accountable for a metastatic phenotype of the pancreatic tumors." (PMID 33946266, 2021). "SDF-1, also named CXCL12, is a mediator of tumor–stromal interactions in different cancer types, including lung and pancreatic cancer, via the CXCR4/CXCL12 axis." (PMID 33673405, 2021). "The invasive border zone of pancreatic tumors is enriched with CD133 + CXCR4 + CSC subpopulation capable of reconstituting primary tumor growth with full tumor differentiation in permissive recipients." (PMID 34453639, 2021). "Studies have now also proposed CD133, CXCR4, and cMet as PaCSCs specific cell markers and demonstrated that cMet positive cells from human pancreatic cancer have increased tumor potential and self-renewal ability." (PMID 33946266, 2021). "For instance, combination of T3 and gemcitabine was reported to down-regulate NF-Kβ activity along with NF-Kβ regulated gene products, such as cyclin D1, c-Myc, VEGF, MMP-9, and CXCR4 in pancreatic cancer." (PMID 34371830, 2021). "Another peptide antagonist to CXCR4, BL-8040 (Motixafortide), has recently been tested in pancreatic cancer as a means of mobilizing bone marrow immune cells to enhance efficacy of the immune checkpoint inhibitor pembrolizumab." (PMID 33805598, 2021). "Exosomal lipids also increase drug resistance in human pancreatic cancer MiaPaCa-2 cells through the C-X-C motif chemokine receptor 4 (CXCR4)/stromal cell derived factor (SDF)-1α signaling pathway." (PMID 32121073, 2020). "The use of CXCR4 as a marker to identify metastatic CSCs is in line with previous studies in pancreatic cancer, in which we showed that CD133+/CXCR4+ CSCs have exclusive tumorigenic and metastasis-initiating capacity." (PMID 32183251, 2020). "In pancreatic cancer, CXCR4 overexpression is a prognostic factor of poor OS; CXCR4 blocking significantly mediates the phenotype of pancreatic cancer cells, inhibiting tumor cell proliferation, invasion, and metastasis." (PMID 32344892, 2020). "Another pathway that contributes to metastasis formation in pancreatic cancer is the C-X-C motif chemokine ligand 12 (CXCL12)/C-X-C chemokine receptor type 4 (CXCR4) axis." (PMID 32069809, 2020). "Collectively, these results suggested that c-Myc regulated the HIF-1α/SDF-1/CXCR4 pathway in pancreatic cancer cells to enhance the antitumor effect of bufalin." (PMID 32362830, 2020). "Pancreatic cancer stem cells do exist and express specific markers including CXCR4, ABCG2, and CD44." (PMID 32210079, 2020).
pancreatic cancer (continued). "Further, c-Myc knockdown decreased the expression of HIF-1α/SDF-1/CXCR4 and enhanced the antitumor effect of bufalin in pancreatic cancer cells." (PMID 32362830, 2020). "CXCR4 is upregulated in pancreatic cancer, colon cancer, ovarian cancer, lymphoma, medulloblastoma, and glioma, which suggests a critical role for CXCR4 in these cancers." (PMID 32635336, 2020). "Downregulation of c-Myc enhanced the antitumor activity of bufalin in pancreatic cancer cells by suppressing the HIF-1α/SDF-1/CXCR4 pathway." (PMID 32362830, 2020). "Recent evidence has shown CXCR4-dependent mTOR signaling in pancreatic cancer, gastric cancer, and T-cell leukemia cells; in fact, CXCR4 and mTOR inhibitors have been reported to impair human renal cancer migration." (PMID 32260318, 2020). "The study reported reduced tumor growth with gemcitabine alone or in combination with a CXCR4 antagonist (AMD3100) or hedgehog inhibitor (GDC-0449) in orthotopic pancreatic tumor-bearing mice." (PMID 33198082, 2020). "Further, previous studies have demonstrated that CXCR4 was highly expressed in pancreatic cancer, and the elevated levels of SDF-1 and CXCR4 were associated with poor prognosis." (PMID 32362830, 2020). "A recent study demonstrated that overexpression of the CXCR4 ligand, SDF-1 in gastric cells can induce myofibroblast expansion and is consistent with the role of CXCR4 in pancreatic cancer." (PMID 31663852, 2019). "In the case of breast and pancreatic cancer cells, butein downregulated chemokine receptor CXCR4 expression and acted via suppression of NF-κB." (PMID 31759370, 2019). "In particular, according to immunohistochemistry data, 56.7% of pancreatic cancer tissues, 50.0% of para-cancerous tissues, and 53.3% of pancreas surrounding lymph nodes express CXCR4 compared to 18,3% of the normal pancreatic tissues." (PMID 31275385, 2019). "The CXCL12/CXCR4 axis seems to play an important role in the processes of invasion, proliferation, migration, metastasis, and angiogenesis in pancreatic cancer." (PMID 31275385, 2019). "Pancreatic cancer, neuroblastoma cells, and glioblastoma also express both CXCR4 and SDF-1 proteins." (PMID 31744214, 2019). "In conclusion, data show that CXCL12/CXCR4/ACKR3 axis is involved in keeping the communication between pancreatic cancer and its microenvironment." (PMID 31275385, 2019). "Radiation exposure increased CAFs-derived CXCL12, a ligand of the C-X-C Motif Chemokine Receptor 4(CXCR4) in pancreatic cancer cells." (PMID 31101063, 2019). "Our results revealed that the SDF-1/CXCR4/SATB-1 axis is vital to acceleration of the malignant progression and the gemcitabine resistance of pancreatic cancer cells and is associated with poor prognosis in PDAC patients." (PMID 30337520, 2018). "Our study provides the first evidence of the association of the SDF-1/CXCR4/SATB-1 axis with PDAC malignant progression and CAF maintenance, suggesting a potential new target of clinical interventions for pancreatic cancer patients." (PMID 30337520, 2018). "Our data also indicated CAFs highly secreted SDF-1 compared with NAFs, which specifically binds to CXCR4 in pancreatic cancer cells and subsequently upregulates the expression of SATB-1 in pancreatic cancer cells." (PMID 30337520, 2018). "In conclusion, these data demonstrated that CAFs upregulated the expression level of SATB-1 in pancreatic cancer cells through the SDF-1/CXCR4 axis." (PMID 30337520, 2018). "In preclinical studies, overexpression of CXCR4 has been demonstrated to dramatically increase lung and liver metastases of murine pancreatic cancer in tail vein metastasis assays in nude mice." (PMID 30622535, 2018). "Interaction of SDF-1 with CXCR4 induces EMT in pancreatic cancer cells, allowing them to migrate along gradients of SDF-1 generated by PSCs." (PMID 29903049, 2018). "Pancreatic cancer cells express high levels of the SDF-1 receptor C-X-C chemokine receptor 4 (CXCR4)." (PMID 29903049, 2018).
pancreatic cancer (continued). "In this study, we demonstrated that SDF-1, also known as C-X-C motif chemokine 12 (CXCL12), secreted by CAFs upregulated SATB-1 expression in pancreatic cancer cells via the SDF-1/CXCR4 axis." (PMID 30337520, 2018). "CXCR4 is the only receptor that is expressed in the normal pancreas, PC cells, and all pancreatic tumor specimens." (PMID 27974694, 2017). "Elimination of CD133+CXCR4+ pancreatic cancer cells significantly reduced the metastatic potential of pancreatic cancer." (PMID 28845161, 2017). "The PANCALYZE trail aims to predict the clinical course of pancreatic cancer on the basis of CXCR4, SMAD4, SOX9 and IFIT3 expression." (PMID 28356064, 2017). "A previous study revealed that CXCL12 specifically signals through CXCR4, a member of the GPCRs to activate Akt and ERK and subsequently phosphorylate IκBα, causing activation of NF-κB signaling in pancreatic cancer cells." (PMID 28288630, 2017). "When pancreatic carcinoma cells are depleted of CD133+CXCR4+, the metastatic potential of cancer cells is abrogated without affecting their tumorigenic potential." (PMID 27974675, 2017). "For example, the CXCR4 blocking mAb inhibits the migration of melanoma or pancreatic cancer cells towards Ad-CM by 40%." (PMID 26756352, 2016). "Like IR, SDF-1 occupation of the G protein coupled chemokine receptor CXCR4 induces Ca2+ signaling and migration/invasion in glioblastoma and pancreatic cancer." (PMID 26893360, 2016). "Previously, we have shown that PAUF induces expression of CXCR4 on pancreatic cancer cells and dendritic cells." (PMID 27322081, 2016). "A subpopulation of migrating CD133+CXCR4+ cancer stem cells contributed to pancreatic cancer metastasis." (PMID 27007162, 2016). "In this regard, some studies have demonstrated that inhibition of CXCR4 with AMD3100 improves T-cell responses in pancreatic cancer or prevents immune suppression in UV-induced skin cancer." (PMID 27590504, 2016). "In that regard, we have previously demonstrated a role of gemcitabine-induced CXCR4 signaling as a counter-defense mechanism, which also promoted invasiveness of pancreatic cancer (PC) cells." (PMID 25970774, 2015). "Here, we explored the roles of pancreatic stellate cells (PSCs) and the SDF-1α/CXCR4 axis in pancreatic cancer chemoresitance." (PMID 25609203, 2015). "CD133+CXCR4+ cells derived from an immortalized pancreatic tumor cell line were shown to metastasize in vivo as compared with the CD133+CXCR4− cell subset." (PMID 25829252, 2015). "SDF-1/CXCR4 are thought to promote pancreatic cancer cell invasion by upregulating the expression and activity of MMP-2." (PMID 26213494, 2015). "In the present study, we investigated the roles and mechanisms of PSCs and the SDF-1α/CXCR4 biological axis in GEM chemoresistance in pancreatic cancer." (PMID 25609203, 2015). "Immunohistochemical staining results revealed that CXCR4 elevation correlated with PNI in 78 pancreatic cancer samples." (PMID 25605248, 2015). "After carefully reading these 361 abstracts we found 20 studies that focused on the expression of CXCR4 in pancreatic cancer." (PMID 26091099, 2015). "CXCR4 expression was significantly higher in the pancreatic tumor tissues compared with the normal pancreas." (PMID 25605248, 2015). "In this study, we demonstrated that GSK3β induced PANC1 pancreatic cancer cell invasion via the CXCR4/MMP-2 pathway." (PMID 26213494, 2015). "Recent research showed that the CXCR4 inhibitor plerixafor was effective in blocking the metastatic potential of pancreatic cancer in a mouse model, indicating once more a potential role for fucoidan fractions to be investigated in this application." (PMID 26389927, 2015). "The results showed that the activation of the CXCL12/CXCR4 axis significantly increased pancreatic cancer cells invasion and promoted the outgrowth of the dorsal root ganglia." (PMID 25605248, 2015).
pancreatic cancer (continued). "The results from both in vitro and in vivo studies have revealed that the stroma-induced CXCL12/CXCR4 axis is involved in pancreatic cancer metastasis through migration, invasion, and angiogenesis/lymphangiogenesis." (PMID 25679210, 2015). "Here, we expanded this preliminary finding and verified that Nodal enhances CXCR4 expression in pancreatic cancer cells via the Smad2/3 pathway in vitro." (PMID 25557170, 2015). "In this study, we show that the CXCL12/CXCR4 axis plays a pivotal role in the neurotropism of pancreatic cancer cells to local peripheral nerves." (PMID 25605248, 2015). "This study provides further insight into the molecular mechanism of GSK3β-induced pancreatic cancer invasion, and will allow exploration of novel therapeutic strategies for pancreatic cancer that target GSK3β and/or CXCR4/MMP-2." (PMID 26213494, 2015). "In pancreatic cancer, a subset of cells expressing CXCR4 was identified as an important determining factor for the metastatic phenotype of individual tumors." (PMID 25251539, 2014). "Correlative pathological and cell culture analyses suggest the chemokine receptor CXCR4 plays a biological role in pancreatic cancer progression." (PMID 24594697, 2014). "Specifically CD133 + CXCR4+ cancer cells had a high metastatic capacity in liver metastases of colorectal tumors, metastatic pancreatic cancers, while overexpression of CD133, CD44v6 and human tissue factor was associated with pancreatic carcinoma metastasis." (PMID 25399490, 2014). "More recently, high CXCR4 expression has been demonstrated in prostate, lung and pancreatic cancer stem cells, but the full extent of its role in cancer has not been elucidated." (PMID 24583601, 2014). "Future studies are needed to determine if RGS16 can inhibit cell migration and invasion through other pathways such as the SDF-1/CxCR4 pathway which is deregulated in pancreatic cancer." (PMID 25568667, 2014). "Various forms of CEA, integrins, BRCA1, and tumor-associated glycoprotein-17 (TAG-17) are overexpressed on pancreatic tumor cells while c-MET, EpCAM, and CXCR-4 are also used as pancreatic cancer stem cell markers." (PMID 25157372, 2014). "Studies have shown that CXCR4 is involved in pancreatic cancer progression through the promotion of angiogenesis." (PMID 23761820, 2013). "Since CXCR4 appears to have an important role in the pathogenesis and progression of pancreatic cancer, our work has important clinical implications in the identification of a novel therapeutic use for these established anti-malarial agents." (PMID 22319600, 2012). "Our study shows that the safe and efficacious anti-malarial drugs chloroquine and hydroxychloroquine are effective CXCR4 antagonists that suppress pancreatic cancer cell proliferation." (PMID 22319600, 2012). "Despite increasing evidence to the importance of CXCR4 in pancreatic cancer and other malignancies, antagonists to CXCR4 that are safe and effective for clinical use remain lacking." (PMID 22319600, 2012). "Next, we observed consistent increases in ERK1/2 phosphorylation after exposure to CXCL12 or CXCL11, a CXCR7 agonist, in pancreatic cancer cell lines co-expressing CXCR4/CXCR7." (PMID 22472349, 2012). "To define the role of CXCL12 and CXCR4 in the progression of pancreatic cancer, we analyzed the association of expression profiles of CXCL12 and CXCR4 with tumor grade and stage." (PMID 23181100, 2012). "For example, integrin-mediated pancreatic cancer cell migration at LN was found to up-regulate CXCR4 and IL-8 expression and responsiveness to CXCL12 stimulation." (PMID 22253872, 2012). "This study reports the influence of CXCL12 and its receptor CXCR4 on the progression of pancreatic cancer and highlights the correlation between the CXCL12/CXCR4 axis and the organ-specific metastasis of pancreatic adenocarcinoma (PAC)." (PMID 23181100, 2012).
pancreatic cancer (continued). "Historically safe in humans, chloroquine and hydroxychloroquine appear to be promising agents to safely and effectively target CXCR4 in patients with pancreatic cancer." (PMID 22319600, 2012). "The CSCs co-expressing CXCR4 were cancer cells with a migratory and invasive phenotype in pancreatic cancer." (PMID 22871210, 2012). "Among several novel discoveries in this investigation, we identified high frequency of CXCR4/CXCR7 co-expression in human pancreatic cancer tissues and cell lines." (PMID 22472349, 2012). "First, we discovered frequent CXCR4/CXCR7 co-expression in human pancreatic cancer tissues and cell lines." (PMID 22472349, 2012). "The paratumorous vessels and neural tissue with positive CXCL12 and CXCR4 expression were invaded by CXCL12-positive pancreatic cancer cells." (PMID 23181100, 2012). "A subpopulation of CSCs overexpressing the cytokine receptor 4 (CXCR4) is essential for pancreatic tumor metastasis." (PMID 22626610, 2012). "We evaluated these compounds in pancreatic cancer cells in vitro and observed specific antagonism of CXCR4-mediated signaling and cell proliferation." (PMID 22319600, 2012). "First, we discovered that pancreatic cancer cells co-expressing CXCR4/CXCR7 had increased levels of ERK phosphorylation and K-Ras activity when exposed to CXCL12." (PMID 22472349, 2012). "In pancreatic cancer and melanoma, CXCR4 expression is regulated by DNA methylation within its promoter region." (PMID 22220212, 2011). "Their work demonstrated that CXCR4 is regulated by DNA methylation in human pancreatic cancer cell lines within the TSS region, which contains the majority of the methylated CpG dinucleotides." (PMID 22220212, 2011). "The CXCR4 gene has been shown to be epigenetically regulated in endometrial carcinoma, melanoma, colonic carcinoma and pancreatic cancer." (PMID 22220212, 2011). "Collectively, these data suggest that CD133+CXCR4+ cancer stem cells determine the metastasis and represent the migrating cancer stem cells of pancreatic cancer." (PMID 21542915, 2011). "In CD133+ pancreatic cancer stem cells, the CXCR4+ subpopulation is more invasive than autologous CXCR4− subpopulation." (PMID 21826251, 2011). "This region was shown to contain 19 CpGs, which were used to determine the methylation pattern of the CXCR4 gene and correlates this pattern with CXCR4 gene silencing in human pancreatic cancer cell lines." (PMID 22220212, 2011). "Earlier it has been shown that CXCR4 is overexpressed in pancreatic tumour tissues and premalignant lesions." (PMID 21045835, 2010). "Our data show that all pancreatic cancer cell lines examined express CXCR4 and low levels of CXCL12 (13–230 pg per ml per 106 cells)." (PMID 21045835, 2010). "CXCR4 expression is elevated in majority of pancreatic cancer tissues and precancerous lesions, suggesting its role in pancreatic cancer pathogenesis." (PMID 21045835, 2010). "We observed that all the pancreatic cancer cell lines tested expressed CXCR4, but low levels of CXCL12." (PMID 21045835, 2010). "CXCL12, a ligand for CXCR4, is also abundantly produced by neighbouring stromal cells and activation of CXCR4-expressing pancreatic cancer cells by CXCL12 leads to enhanced chemotaxis, transendothelial migration, and Matrigel invasion." (PMID 21045835, 2010). "Here, we examined the expression of CXCR4 and its ligand CXCL12 by immunoblot and enzyme-linked immunosorbant assay (ELISA), respectively, in a panel of 12 pancreatic cancer cell lines." (PMID 21045835, 2010). "Altogether, these observations indicate an important role of CXCR4 signalling in pancreatic cancer survival, proliferation, invasion, and metastasis, suggesting this signalling axis as a potential target for cancer therapy." (PMID 21045835, 2010). "In conclusion, CXCR4 immunostaining of pancreatic cancer can serve as a prognostic marker for survival after curative surgery." (PMID 19352387, 2009).